PGLYRP4 (peptidoglycan recognition protein 4)
Description:
Pattern receptor that binds to murein peptidoglycans (PGN) of Gram-positive bacteria. Has bactericidal activity towards Gram-positive bacteria. May kill Gram-positive bacteria by interfering with peptidoglycan biosynthesis. Also binds to Gram-negative bacteria, and has bacteriostatic activity towards Gram-negative bacteria. Plays a role in innate immunity.
Synonyms: PGLYRPIbeta; PGRPIB; SBBI67; PGRP-Ibeta
Tractability: Antibody: UniProt places it where antibodies can reach, with high confidence; UniProt predicts a signal peptide or a membrane-spanning region; its Gene Ontology location is reachable by antibodies, with medium confidence; the Human Protein Atlas places it where antibodies can reach.
Gene: Protein-coding gene on chromosome 1 (153,330,120 to 153,348,841, reverse strand). Ensembl gene ENSG00000163218.
Subcellular location: Secreted
Subcellular location (Human Protein Atlas): Plasma membrane; Vesicles; Predicted to be secreted
Pathways (Reactome):
Immune System: Antimicrobial peptides
Gene Ontology:
Molecular function: peptidoglycan binding; peptidoglycan immune receptor activity; protein heterodimerization activity; N-acetylmuramoyl-L-alanine amidase activity; zinc ion binding
Biological process: antimicrobial humoral immune response mediated by antimicrobial peptide; defense response to Gram-positive bacterium; detection of bacterium; killing of cells of another organism; immune response; innate immune response; peptidoglycan catabolic process
Cellular component: protein-containing complex; membrane; extracellular region
Genetic constraint (gnomAD): Loss-of-function variants: 31 observed, 32.84 expected, observed/expected ratio (o/e) 0.94, 90% interval 0.71 to 1.27. The upper end of that interval is the gene's LOEUF score, 1.27, which puts it in group 5 of 6, group 1 being the genes least tolerant of losing a copy. Missense variants: 423 observed, 440.2 expected, observed/expected ratio (o/e) 0.96, 90% interval 0.89 to 1.04. Synonymous variants: 186 observed, 181.5 expected, observed/expected ratio (o/e) 1.02, 90% interval 0.91 to 1.16.
Homologues: Orthologues: chimpanzee PGLYRP4 (98% identical), macaque PGLYRP4 (95% identical), mouse Pglyrp4 (76% identical), pig PGLYRP4 (73% identical), rat Pglyrp4 (73% identical), Drosophila melanogaster PGRP-LE (23% identical), Drosophila melanogaster PGRP-SB1 (21% identical), Drosophila melanogaster PGRP-SA (20% identical), Drosophila melanogaster PGRP-LF (19% identical), Drosophila melanogaster PGRP-SD (17% identical), Drosophila melanogaster PGRP-SB2 (16% identical), Drosophila melanogaster PGRP-SC2 (16% identical), and 3 more. Paralogues in human: PGLYRP3 (62% identical), PGLYRP2 (27% identical), PGLYRP1 (21% identical).
Diseases named in the same sentence as PGLYRP4 in open-access papers:
PGLYRP4 is named in the same sentence as 15 diseases in open-access papers, as found by Europe PMC text mining. Sharing a sentence is not in itself a finding about the gene and the disease. The quoted sentences say what the papers report.
psoriasis (4 papers, 2011 to 2021). An autoimmune condition characterized by red, well-delineated plaques with silvery scales that are usually on the extensor surfaces and scalp. "Also, human Pglyrp3 and Pglyrp4 are genetically associated with psoriasis." (PMID 26727498, 2016). "Thus, the role of PGLYRPs in animal models of inflammatory diseases is well established, but the role of PGLYRPs in human diseases remains unknown, except for the previously reported association of PGLYRP3 and PGLYRP4 with psoriasis." (PMID 23840689, 2013). "The PGLYRP4 gene is located on chromosome 1 (1q21.3) and is directly implicated in the physiopathogenesis of psoriasis, as it plays an essential role in innate immunity; for this reason, it is also known as PSORS4 (susceptibility to psoriasis 4)." (PMID 33921427, 2021). "PGLYRP2 protects mice against psoriasis-like skin inflammation and is required for the development of experimental arthritis, whereas PGLYRP3 and PGLYRP4 protect mice against atopic dermatitis." (PMID 23840689, 2013).
atopic dermatitis (3 papers, 2011 to 2021). "By contrast, atopic dermatitis-sensitive Pglyrp-deficient mice (Pglyrp3−/−, Pglyrp4−/− and Pglyrp2−/−Pglyrp3−/− mice) all had lower expression of FoxP3 mRNA in the affected ears compared to WT mice." (PMID 21949809, 2011). "Pglyrp4, which has been reported to influence the innate and adaptive immunity as well as atopic dermatitis through modulation of Treg versus Th17 activity." (PMID 34295313, 2021). "Atopic dermatitis-sensitive mice (Pglyrp3−/−, Pglyrp4−/−, and Pglyrp2−/−Pglyrp3−/− mice) had increased expression of genes characteristic of B cells and T cells." (PMID 21949809, 2011). "We demonstrate here that Pglyrp3−/− and Pglyrp4−/− mice develop more severe oxazolone-induced atopic dermatitis than WT mice." (PMID 21949809, 2011). "In summary, our results indicate that in WT mice Pglyrp3 and Pglyrp4 promote efficient population of the skin with Treg cells in the experimental model of atopic dermatitis." (PMID 21949809, 2011). "Therefore, our results indicate that Pglyrp3 and Pglyrp4 are involved in controlling multiple functions of Treg and Th17 cells in the skin in atopic dermatitis." (PMID 21949809, 2011). "Because WT mice were able to limit skin inflammation in the atopic dermatitis model more effectively than Pglyrp3−/− and Pglyrp4−/− mice, we then tested whether this difference is due to impaired generation or function of regulatory T cells (CD4+FoxP3+ Treg) in Pglyrp-deficient mice." (PMID 21949809, 2011). "Pglyrp3−/− and Pglyrp4−/− mice (but not Pglyrp2−/− mice) develop more severe oxazolone-induced atopic dermatitis than wild type (WT) mice." (PMID 21949809, 2011). "Our results show that Pglyrp3−/− and Pglyrp4−/− mice (but not Pglyrp2−/− mice) are more sensitive to the development of experimental atopic dermatitis than wild type (WT) mice." (PMID 21949809, 2011).
bacteremia (2 papers, 2019 to 2021). "Mice lacking PGLYRP4 displayed an enhanced bacterial clearance in the lungs, and fewer mice developed bacteremia." (PMID 31616404, 2019).
COVID-19 (2 papers, 2021 to 2025). A disease caused by infection with severe acute respiratory syndrome coronavirus 2. "Novel transcriptional signatures of the SARS-CoV-2 virus, including PGLYRP4 and HEPHL1, were detected, and their prospective mechanisms in the pathogenesis of COVID-19 and associated complications were suggested." (PMID 34441862, 2021). "Examining hub genes, like PGLYRP4 and HEPHL1, that have been connected to COVID-19 may shed light on how colistin affects the immune system." (PMID 40428842, 2025). "The novel hub gene signature that was detected in our study, including PGLYRP4 and HEPHL1, may shed light on the pathogenesis of COVID-19, holding promise for future prognostic and therapeutic approaches." (PMID 34441862, 2021).
pneumococcal pneumonia (2 papers, 2019 to 2021). A febrile disease caused by STREPTOCOCCUS PNEUMONIAE. "To analyze the so far unknown effects of PGLYRP4 on lung infections, and investigate possible gut-lung immune interactions, we investigated the influence of PGLYRP4-deficiency on the development and outcome of pneumococcal pneumonia." (PMID 31616404, 2019). "Therefore, wild type (WT) and PGLYRP4-deficient (PGLYRP4KO) mice were analyzed in an in vivo and in vitro experimental setting to examine the influence of PGLYRP4 on the course of pneumococcal pneumonia." (PMID 31616404, 2019).
colitis (1 paper, 2019). Inflammation of the colon. "Interestingly, it was reported that PGLYRP-2−/− and PGLYRP-3−/− mice were highly sensitive to DSS-induced colitis than PGLYRP-1−/− and PGLYRP-4−/− mice, which had intermediate or low sensitivity, respectively." (PMID 31416116, 2019).
contact dermatitis (1 paper, 2011). An inflammatory skin condition caused by direct contact between the skin and either an irritating substance or an allergen. "Our results show that Pglyrp1 (and other Pglyrps to a lesser extent) promotes Th1 responses, because Pglyrp1−/− mice (and also Pglyrp2−/− and Pglyrp4−/− mice) have reduced inflammation in oxazolone-induced contact dermatitis." (PMID 21949809, 2011).
Crohn disease (1 paper, 2020). A gastrointestinal disorder characterized by chronic inflammation involving all layers of the intestinal wall, noncaseating granulomas affecting the intestinal wall and regional lymph nodes, and transmural fibrosis. "Additionally, variants in PGLYRP4 have been associated with onset age of Crohn's disease, while rs10888557 has also been associated with ulcerative colitis risk in a Greek population." (PMID 33328979, 2020).
eczema (1 paper, 2023). "For instance, we found that psoriatic skin eSNPs and eczema risk loci colocalize at PGLYRP4, which has been linked to eczema development in mouse models through Th17 activation." (PMID 37805522, 2023). "The eGene that most strongly colocalized with eczema risk alleles was PGLYRP4 (PP.H4 = 0.989), which is an innate immunity-related gene encoding for peptidoglycan recognition protein." (PMID 37805522, 2023). "The deficiency of Pglyrp4 in mice has been reported to be involved in the development of eczema through reduced recruitment of Tregs and increased activation of Th17 responses." (PMID 37805522, 2023).
pneumonia (1 paper, 2019). An acute, acute and chronic, or chronic inflammation focally or diffusely affecting the lung parenchyma, caused by an infection in one or both of the lungs (by bacteria, viruses, fungi, or mycoplasma.). "Because of this broad spectrum of known antibacterial activity, but unknown activity against S. pneumoniae, we investigated the in vivo effects of PGLYRP4 in a PGLYRP4-deficient mouse pneumonia model." (PMID 31616404, 2019).
infection (3 papers, 2019 to 2025). The state of being infected such as from the introduction of a foreign agent such as serum, vaccine, antigenic substance or organism. "Upon infection with pneumococci, Pglyrp4 was significantly downregulated to approximately 40% of the untreated control value in AEC and increased significantly 4-fold in AMΦs." (PMID 31616404, 2019). "This suggests that PGLYRP4 may play a role as a molecular cue in Shigella infection process, contributing to the precise regulation of the Shigella virulence system based on environmental conditions imposed by tissue location and stage of infection." (PMID 41208093, 2025). "In this study, we investigated a novel mechanism by which Shigella exploits the PGLYRP4 protein, a component of the host's innate immune system, to increase its virulence at the site of infection without affecting bacterial viability." (PMID 41208093, 2025).
PGLYRP4 also shares sentences with these, for which no sentence is quoted: Bordetella pertussis infection (1 paper); cancer (1); severe acute respiratory syndrome (1); ulcerative colitis (1).